TNFAIP3 (TNF alpha induced protein 3)
Diseases named in the same sentence as TNFAIP3 in open-access papers (continued):
Sharing a sentence is not in itself a finding about the gene and the disease.
psoriasis (continued). "Genome-wide association surveys have revealed that TNFAIP3 and TNIP1 were key biomarkers for psoriasis." (PMID 32398022, 2020). "TNFAIP3 mRNA expression in PBMCs was significantly lower in patients with psoriasis (mean ± SD = 0.44 ± 0.25) compared with normal subjects (mean ± SD = 1.00 ± 0.82; P < 0.01)." (PMID 32280718, 2020). "After that, numerous studies on the association of single nucleotide polymorphisms in TNFAIP3 and TNIP1 with the risk of psoriasis have conducted." (PMID 32398022, 2020). "Here, we intended to conduct a survey on the association between TNFAIP3 and TNIP1 gene polymorphisms and psoriasis risk." (PMID 32398022, 2020). "Meanwhile, the protective anti-inflammatory role of TNFAIP3 against psoriasis can be plausibly explained by its ability to suppress inflammasome activity and subsequently cell death." (PMID 31120955, 2019). "In the skin network, we identify KDs such as ICAM1, IL15, STAT1, TNFAIP3, and GRB2 to be the network hubs connecting numerous genes in the psoriasis-associated supersets." (PMID 30642337, 2019). "A recent pharmacogenetic study reported that homozygous patients for an SNP rs610604 in TNFAIP3 showed an inferior response to ustekinumab, a biologic used in psoriasis, in comparison with a control group." (PMID 31120955, 2019). "As the actions of TNFAIP3 become more apparent, its role in existent and future therapies for psoriasis becomes clearer." (PMID 31120955, 2019). "Further studies to understand the epigenetic events that affect TNFAIP3 regulation and the correlation between its levels and immunologic features of psoriasis are required." (PMID 31120955, 2019). "The effect of the expression of TNFAIP3 in blood samples and psoriatic skin biopsies from psoriatic patients on the severity of psoriasis was also studied." (PMID 31120955, 2019). "This inverse correlation between TNFAIP3 gene and the severity of psoriasis suggests that increasing the expression and/or function of TNFAIP3 is a promising therapeutic strategy." (PMID 31120955, 2019). "In this study, we demonstrated that the expression of TNFAIP3 gene was altered in psoriasis, as evidenced by a significant down-regulated expression of TNFAIP3 mRNA in blood and skin of psoriatic patients compared to controls (P <0.001)." (PMID 31120955, 2019). "Examination of TNFAIP3 mRNA expression in skin biopsies from patients with psoriasis revealed reduced expression in both involved and uninvolved skin." (PMID 28658319, 2017). "Increasing evidence indicates that genetic mutations in genes such as TNFAIP3, TNIP1, NFKBIA, TRAF3IP2, and CARD14 result in an impaired negative regulation of NF‐κB proinflammatory activity leading to psoriasis." (PMID 28377495, 2017). "Altered expression of TNFAIP3 has been previously reported in other inflammatory disorders like CD, psoriasis, cystic fibrosis and pediatric IBD30, 33–35." (PMID 28842689, 2017). "Regarding the genetic association between psoriasis and autoimmunity, TNF-alpha-induced protein 3 (TNFAIP3) has been shown to be a major candidate." (PMID 26339139, 2015). "Ours is the first study to identify an association between FCGR2A, TNFR1, CD226, TNFAIP3, and CCHCR1 and age at onset of psoriasis." (PMID 26613086, 2015). "Comparison between patients with type I psoriasis and patients with type II psoriasis revealed significant associations for the following genes: FCGR2A, TNFR1, CD226, PSORS6, TNFAIP3, HLA-C, TNF-α, and CCHCR1." (PMID 26613086, 2015). "In addition, the NF-κB inhibitors TNFAIP3 (TNF-α induced protein 3, encoding A20) and TNIP1 (TNFAIP3-interacting protein 1, encoding ABIN1) have been identified as susceptibility loci for psoriasis and keratinocyte-associated genes." (PMID 35075118, 2022). "We tentatively speculate that the level of TNFAIP3 expression targeted by AP-1 is a dynamic fluctuation in the occurrence and development of psoriasis." (PMID 35277199, 2022).
psoriasis (continued). "Similar with TNFAIP3, more than 3 genome-wide association studies (GWAS) indicated that TNIP1 had been implicated in numerous inflammatory disease, including psoriasis, psoriatic arthritis, systemic lupus erythematosus (SLE), systemic sclerosis (SSC), rheumatoid arthritis (RA)." (PMID 32398022, 2020). "Considering that study sample sizes were small and the statistical effect was limited of an individual study, this meta-analysis is meant to provide the most comprehensive and precise evaluation on the association of TNFAIP3 and TNIP1 polymorphisms with psoriasis vulnerability." (PMID 32398022, 2020). "We investigated the immune regulation of TNFAIP3 in the pathogenesis of psoriasis and determined whether it is involved in the antipsoriatic effect of TNF-α antagonists." (PMID 32280718, 2020). "Genetic studies have shown that TNFAIP3 polymorphisms are associated with several autoimmune diseases such as systemic lupus erythematosus (SLE), inflammatory bowel disease (IBD), multiple sclerosis (MS), rheumatoid arthritis (RA), and psoriasis." (PMID 33613524, 2020). "Other studies showed an up-regulation of TNFAIP3 expression in mild cases; this may be explained by the chronic inflammation existing in psoriasis patients." (PMID 31120955, 2019). "This strong expression of TNFAIP3 found in lesional psoriatic skin has been posited to inhibit the NF-κB pathway; however, a strong expression of NF-κB was observed, suggesting that TNFAIP3 is disabled or dysfunctional in patients with psoriasis." (PMID 31120955, 2019). "Additionally, up-regulation of proinflammtory cytokines and chemokines, as well as systemic proinflammatory changes have been detected in epidermis-specific TNFAIP3 knockout mice, in which TNFAIP3 absence exacerbated the severity of experimental psoriasis." (PMID 31120955, 2019). "Therefore, sustained inflammation accounts for the increased TNFAIP3 expression in PBMC of patients with mild psoriasis." (PMID 31120955, 2019). "Psoriasis patients harboring specific TNFAIP3 SNPs respond more effectively to TNF blockade." (PMID 29515565, 2018). "Some of the TNFAIP3 variants found in our population have been reported in other diseases: rs5029937 and F127C with RA and SLE, rs5029939 with SLE and systemic sclerosis, and F127C and rs610604 with psoriasis." (PMID 28791018, 2017). "For example in psoriasis, TNFAIP3 mRNA expression increases during the disease." (PMID 28842689, 2017). "Besides psoriasis, the TNIP1 and TNFAIP3 gene have been associated with systemic lupus erythematosus (SLE)." (PMID 26046540, 2015). "rs191190 in TNFR1 and rs10499194 in TNFAIP3 have been associated with psoriasis, but not with age of onset." (PMID 26613086, 2015). "In humans, single nucleotide polymorphisms (SNPs) of the TNFAIP3 gene have been associated with a range of autoimmune diseases including systemic lupus erythematosus (SLE), rheumatoid arthritis (RA), inflammatory bowel disease, psoriasis and type one diabetes." (PMID 26124703, 2015). "In this study, we focused on the association of five SNPs in TNFAIP3 with VKH disease mainly because they were found to be associated with certain autoimmune or rheumatic disease, including psoriasis, SLE, RA, juvenile idiopathic arthritis and psoriatic arthritis." (PMID 23555688, 2013). "Recently, a genome-wide scan study in 1,409 psoriasis cases and 1,436 controls revealed associations between three genes of the IL-23 pathway (IL23A, IL23R and IL12B), two genes of nuclear factor-κB (NF-κB) pathway (TNIP1 and TNFAIP3) and psoriasis." (PMID 21555979, 2011). "Three of the identified psoriasis risk variants had a stronger association with PsC than PsA (rs12189871 near HLA-C, rs4908742 near TNFRSF9, rs10888503 near LCE3A), whereas two had a stronger association with PsA than PsC (rs12044149 near IL23R, rs9321623 near TNFAIP3)." (PMID 36826011, 2023). "Therefore, this study investigated the immune regulatory effects of TNFAIP3 in psoriasis." (PMID 32280718, 2020).
psoriasis (continued). "Two SNPs near TNFAIP3 (6q23.3) have been reported as associated with celiac disease, with other SNPs in the region being associated with other autoimmune diseases (UC, SLE, RA, psoriasis, multiple sclerosis, Sjögren’s syndrome, primary sclerosing cholangitis)." (PMID 29309429, 2018). "Interestingly, TNFAIP3 has not emerged from AS-specific GWAS, even though it has been implicated in related diseases with clinical overlap, such as psoriasis and inflammatory bowel disease (IBD)." (PMID 28791018, 2017). "At least 36 different loci have been identified as susceptibility loci of psoriasis by GWAS, including the TNIP1 gene, which encodes TNF-α–induced protein 3-interacting protein 1 (TNIP1), as well as the tumor necrosis factor α-induced protein 3 (TNFAIP3) gene, which encodes protein A20." (PMID 26046540, 2015). "Four SNPs were associated with significant decreases in the risk of type I psoriasis (N = 155) compared with type II psoriasis (N = 36), namely, rs191190 (TNFR1; 126.08-fold), rs361525 (TNF-α; 190.76-fold), and rs10499194 and rs6920220 (TNFAIP3; 155.02-fold and 19.14-fold, resp)." (PMID 26613086, 2015). "On the other hand, patient 2 and 3 shared SNPs in NFKBIZ and in TNFAIP3, encoding the IL-17/TRAF6 signaling regulators IKB-ζ and A20, respectively, whose genetic variability could contribute to immune dysregulation and chronic inflammation in psoriasis lesions." (PMID 38495872, 2024). "On the other hand, TNFAIP3, an inhibitor of the NF-kβ pathway was shown to be significantly declined in the IMQ psoriasis induced group." (PMID 37010718, 2023). "It induces the expression of other psoriasis signature genes, such as IL36G, S100A15, DEFB4A, S100A9, CXCL8, TNIP3 (coding TNF-α-induced-protein 3 or TNFAIP3), and LCN2 (by synergy of IL-17C with TNF-α) in keratinocytes." (PMID 36928592, 2023). "Tumor necrosis factor alpha induced protein 3 (TNFAIP3/A20) and TNFAIP3 interacting protein 1 (TNIP1) have been accepted as the related candidate genes for psoriasis." (PMID 33981308, 2021). "We investigated the relative expressions of TNFAIP3, T helper cell differentiation, inflammatory cytokine secretions, and immune pathway activation in the IMQ-induced psoriasis-like dermatitis model." (PMID 32280718, 2020). "To further explore the role of TNFAIP3 in the pathogenesis of psoriasis, we established an IMQ-induced psoriasis-like dermatitis model, which is widely used as a rodent model of psoriasis." (PMID 32280718, 2020). "When taken together with genes (that is, TNIP1, TNFAIP3 and NFKBIA) mapping to known psoriasis loci that are well-appreciated as components of NF-κB signalling, our results further implicate this pathway in the pathophysiology of psoriasis." (PMID 28537254, 2017). "Several SNPs used as IVs in the psoriasis MR analyses are located in or near genes with known immunological and inflammatory functions relevant to both diseases, such as IL23R, IL13, TRIM27, HLA-A, HLA-B, and TNFAIP3." (PMID 41465162, 2025). "Previous studies have shown that the expression of TNFAIP3 is downregulated in non-lesional areas of psoriasis and further downregulated in lesional areas." (PMID 35277199, 2022). "Here, we demonstrated that TNFAIP3 mRNA was expressed at low levels in psoriatic patients and the IMQ-induced psoriasis-like dermatitis model and that TNF-α antagonists increased TNFAIP3 expression and attenuated the severity of psoriasis in the mouse model." (PMID 32280718, 2020). "Perhaps this is not entirely surprising since common variants in TNFAIP3 have also been associated with several autoimmune diseases including SLE, RA, and psoriasis." (PMID 30022980, 2018). "Reduced TNFAIP3 mRNA expression was observed in peripheral blood mononuclear cells (PBMCs) in SLE and RA patients and in disease-affected organs, e.g., in colon or skin biopsies from CD and psoriasis patients compared to healthy tissues." (PMID 29515565, 2018).
psoriasis (continued). "Meanwhile, TNFAIP3 protein has been found down-regulated in lesional epidermis of patients with psoriasis and atopic dermatitis, signifying that absence of TNFAIP3 expression in keratinocytes triggers the generation of inflammatory skin conditions including psoriasis." (PMID 31120955, 2019). "Moreover, a significant negative correlation was found between TNFAIP3 mRNA in psoriatic tissue and psoriasis area severity index values (rs = -0.382, P-value = 0.037)." (PMID 31120955, 2019). "Additionally, the fact that NF-κB stimulates TNFAIP3 mRNA expression in response to inflammation confirms that low TNFAIP3 expression acts as a driver rather than a result of the inflammatory process seen in psoriasis." (PMID 31120955, 2019). "Moreover, rs1801274 in FCGR2A and rs6920220 in TNFAIP3 have not been studied in patients with psoriasis according to age of onset." (PMID 26613086, 2015). "In addition, rs610604 (TNFAIP3) and rs17728338 (TNIP1), but not rs2066808 (IL23R) and rs397211 (IL1RN), were associated with psoriasis in a case-control study." (PMID 24069534, 2013).
rheumatoid arthritis (69 papers, 2009 to 2026). A chronic, systemic autoimmune disorder characterized by inflammation in the synovial membranes and articular surfaces. "Associations between TNFAIP3 and various autoimmune diseases, including SS, rheumatoid arthritis, systemic lupus erythematosus (SLE), and systemic sclerosis, have been documented." (PMID 38933282, 2024). "Deletion of the rheumatoid arthritis susceptibility gene A20/Tnfaip3 in mice [i.e., the A20(myel-KO) mice] induced spontaneous rheumatoid arthritis." (PMID 36669831, 2023). "TNFAIP3 Phe127Cys (rs2230926) is a single-nucleotide polymorphism associated with development of autoimmune diseases such as rheumatoid arthritis, SLE, and type 1 diabetes mellitus (DM)." (PMID 34899744, 2021). "In this context, the rs6920220 SNP, located in a noncoding region upstream of TNFAIP3, has been linked to an increased risk of rheumatoid arthritis, lupus erythematosus, type II psoriasis, Sjögren’s syndrome, and type I diabetes." (PMID 30813592, 2019). "TNFAIP3, also known as A20, has been associated with psoriasis, rheumatoid arthritis, type 1 diabetes mellitus, systemic lupus erythematosus, and CD." (PMID 32099610, 2019). "Single nucleotide polymorphisms (SNPs) in TNFAIP3 encoding A20 confer risk to several inflammatory or autoimmune diseases, such as psoriasis, Crohn's disease, rheumatoid arthritis, and systemic lupus erythematosus." (PMID 31156649, 2019). "Our results also do not explain both risk and protective associations located ∼200 kb upstream of TNFAIP3 reported most robustly in rheumatoid arthritis and celiac disease but also in SLE and inflammatory bowel disease." (PMID 24039598, 2013). "Besides, through phenotype screening, we identified an association between TNFAIP3 (rs5029937) and various autoimmune diseases, such as rheumatoid arthritis and SLE, consistent with previous research." (PMID 38573314, 2024). "Mutations in the TNFAIP3 gene are implicated in various immune-related diseases, such as Behçet’s disease, polyarticular juvenile idiopathic arthritis, autoimmune thyroiditis, autoimmune hepatitis, and rheumatoid arthritis." (PMID 39125844, 2024). "Rs10499194 and rs2230926 polymorphisms in the TNFAIP3 gene region may be susceptibility factors for rheumatoid arthritis in the northern Chinese Han population." (PMID 24884566, 2014). "To date, many studies explored the associations between tumor necrosis factor alpha inducible protein 3 (TNFAIP3) gene rs6920220, rs2230926, and rs5029937 polymorphisms and the risk of rheumatoid arthritis (RA), but with contradictory results." (PMID 28199970, 2017). "In humans, polymorphisms in or near the TNFAIP3/A20 gene have been linked to various inflammatory disorders, including systemic lupus erythematosus (SLE) and rheumatoid arthritis (RA)." (PMID 37865713, 2023). "and his team have demonstrated A20 (Tnfaip3) is a negative regulator of Toll like receptor (TLR) in rheumatoid arthritis." (PMID 35873150, 2022). "This suggestion is also based on our previous finding on the different SNP distribution of TNFAIP3 in CDS in patients with rheumatoid arthritis in comparison with patients from other countries." (PMID 34526012, 2021). "For instance, it has been found that the gene expression of TNFAIP3 was decreased in peripheral blood mononuclear cells of rheumatoid arthritis patients as compared with healthy control." (PMID 34500744, 2021). "Good examples of known shared risk loci in IMDs are PTPN22, IL23R and TNFAIP3, which have allowed the repositioning of anti-TNF and anti-IL-12/IL-23 therapies to be used in rheumatoid arthritis (RA) and systemic lupus erythematosus (SLE), among others." (PMID 33317201, 2020). "Here, we analyzed two TNFAIP3 polymorphisms in Italian patients with systemic lupus erythematosus (SLE), rheumatoid arthritis (RA), and primary Sjogren's syndrome (pSS), to verify if the genetic variability of TNFAIP3 gene is involved in genetic predisposition to AIDs also in the Italian population." (PMID 31534975, 2019).